FOXO1 (forkhead box O1)
Diseases named in the same sentence as FOXO1 in open-access papers (continued):
Sharing a sentence is not in itself a finding about the gene and the disease.
glioma (continued). "There are various upregulated miRNAs, including miR-21, miR-28-5p, miR-196a-5p, miR-374a, miR-486–5p, and miR-5188 in different glioma cell lines that target 3′ UTR of FOXO1 mRNA." (PMID 37821870, 2023). "An overview of literature has demonstrated that FOXO1 has a controversial role in tumorgenesis of gliomas." (PMID 37821870, 2023). "Forkhead box O1 has been reported to promote temozolomide resistance in gliomas through modulation of RFC2." (PMID 37251536, 2023). "Similar to FOXM1, various studies have identified upstream/downstream regulators of FOXO1 in gliomas." (PMID 37821870, 2023). "Later, further research conducted on TCGA-LGG and GTEx brain databases showed that low-grade gliomas have a significantly upregulated FOXO1 expression." (PMID 37821870, 2023). "TRIM47 has a role in promoting the development of glioma by ubiquitination and degradation of FOXO1." (PMID 37367937, 2023). "Altogether, focusing on the tumor suppressor role of FOXO1, most of the anticancer drugs that affect FOXO1 in glioma increase its expression, except EMAP-II and Progesterone, which their efficacy is dose or/and time-dependent." (PMID 37821870, 2023). "MicroRNA-21 derived from T. gondii infected microglial cells promoted the growth of U86 glioma cells through suppressing antitumoral genes (FoxO1, PTEN, and PDCD4)." (PMID 37818043, 2023). "Recently, a study demonstrated that the LITAF expression is decreased in glioma tissues, which likely enhances the radiosensitivity of glioma cells through upregulating the FoxO1 pathway." (PMID 35429411, 2022). "We observed the possible role of altered exosomal miR-21 in the growth of U87 glioma cells through the nuclear retention of FoxO1/p27 targeted by overexpressed miR-21." (PMID 36180486, 2022). "For example, metabolic stress in glioma cells resulted in the induction of cyclin F in a FOXO1-dependent manner that leads to RBPJ proteolysis." (PMID 36293193, 2022). "Recent literature has revealed that FOXO1 enhances etoposide-induced cytotoxicity against glioma cells." (PMID 35141227, 2021). "In the presence of FOXO1, glioma cell proliferation is inhibited, but addition of PID1 allows the proliferation ability to return to control levels." (PMID 35141227, 2021). "For further verification, we displayed that FOXO1 was poorly expressed in glioma tissues relative to normal brain tissues." (PMID 35141227, 2021). "c‐JUN and SP1 mRNA levels were elevated in glioma in comparison with those in healthy brain tissues (P < .0001), whereas FOXO1 mRNA levels were down‐regulated in glioma (P = .0049)." (PMID 32902145, 2020). "Our study showed that FOXO1 inhibited cell growth and metastasis in glioma, which are consistent with those in the previous study." (PMID 32902145, 2020). "More recently, well described tumor suppressive lncRNA, GAS5, was described to suppress malignancy of glioma stem cells via a miR-196a-5p/FOXO1 feedback loop and proliferation, migration, and invasion of glioma cells by negative regulation of miR-18a-5p." (PMID 30217088, 2018). "KLF4 protein level was also inversely correlated with FOXO1 protein level in the glioma tissue samples." (PMID 27835585, 2016). "In this study, our findings indicated that FOXO1 expression frequently decreased in glioma tissues and cells." (PMID 27835585, 2016). "Our findings indicated that FOXO1 is frequently down-regulated in glioma and its down-regulation is correlated with glioma progression." (PMID 27835585, 2016). "FOXO1 expression decrease correlated with glioma progression and predicted a worse overall survival of glioma patients." (PMID 27835585, 2016). "Although the tumor suppressive role of FOXO1 has been well characterized for some cancer types, little is known of its biological function and significance in glioma." (PMID 27835585, 2016). "In the present study, we demonstrated the expression pattern, function and clinical significance of FOXO1 in glioma." (PMID 27835585, 2016).
glioma (continued). "Our findings indicated that FOXO1 down-regulation mediated by KLF4 confers to progression of glioma." (PMID 27835585, 2016). "Bioinformatics analysis and experimental results indicated that KLF4 transcriptionally repressed FOXO1 expression in glioma cells." (PMID 27835585, 2016). "Expectedly, KLF4 mRNA level was inversely correlated with FOXO1 mRNA level in glioma tissue samples." (PMID 27835585, 2016). "Our results showed that ectopic FOXO1 expression inhibited glioma cells invasive potential and inhibited glioma cells growth in vitro and in vivo." (PMID 27835585, 2016). "Then, the FOXO1 protein level in a cohort of 73 tissue samples involving 8 normal brain tissue samples and 65 glioma tissue samples with follow-up records, was examined using immunohitochemical staining." (PMID 27835585, 2016). "Here, the objective of the present study was to investigate the expression pattern, function, clinical significance and regulatory mechanism of FOXO1 in glioma." (PMID 27835585, 2016). "Here, we then established stable FOXO1 overexpression glioma cell lines in U87MG and U251MG via transfection with FOXO1 overexpressing plasmid pReceiver-Lv/FOXO1 tested by western blot." (PMID 27835585, 2016). "In order to investigate the role of FOXO1 in glioma, here the FOXO1 mRNA level in the 39 fresh-frozen human primary glioma tissue samples with different grades was examined using qRT-PCR." (PMID 27835585, 2016). "We further confirmed the effect of FOXO1 on proliferation of glioma cells in vivo using nude mice model with glioma xenografts." (PMID 27835585, 2016). "A western blot analysis revealed a decrease in the level of the phosphorylated form of Foxo1 in glioma cells compared with the control cells." (PMID 27733172, 2016). "We found that FOXO1 is frequently down-regulated at both mRNA and protein levels in glioma, and that FOXO1 down-regulation was correlated with glioma progression." (PMID 27835585, 2016). "Our data indicated that FOXO1 expression is down-regulated in glioma tissue samples and cells, and acts as a cancer suppressor." (PMID 27835585, 2016). "To investigate the role of FOXO1 in glioma, we analyzed the correlation of FOXO1 protein level with clinicopathological parameters in the cohort of 65 glioma tissue samples." (PMID 27835585, 2016). "Restored FOXO1 expression inhibited glioma cells invasion and suppressed glioma cells proliferation in vitro and growth in vivo." (PMID 27835585, 2016). "In glioma cells, Foxo1 and Rb1 can be inactivated by hyperphosphorylation, and phosphorylated Foxo1 is exported from the nucleus in a CRM1-dependent manner." (PMID 27733172, 2016). "Here, we found that FOXO1 is frequently down-regulated at both mRNA and protein levels in glioma, suggesting FOXO1 expression should be regulated at transcriptional level." (PMID 27835585, 2016). "FOXO1 activation inhibits tumor cell survival by inducing apoptosis in glioma cells through upregulating pro-apoptotic factors." (PMID 25749387, 2015). "In vivo experiments have shown intratumoral injection with AdFOXO1; AAA (a mutant FOXO1 which cannot be negatively regulated by PI3K-Akt phosphorylation) can improve survival of mice implanted with glioma cell in brain." (PMID 23874926, 2013). "It was recently shown that FOXO1 can effectively induce glioma cell death and inhibit tumor growth through cell cycle arrest and apoptosis." (PMID 23874926, 2013). "Cytoplasmic FOXO1 expression in high-grade glioma was significantly higher than that of low-grade glioma (median H-score: 80 versus 10, P = 0.005) while nuclear FOXO1 expression was comparable in both (median H-score: 40 versus 40, P = 0.471)." (PMID 23874926, 2013). "It has been demonstrated that targeting FOXO1 can effectively induce glioma cell death in vitro and inhibit tumor growth in vivo." (PMID 23874926, 2013). "In glioma, constitutive nuclear FOXO1 expression can induce cell death in vitro and prolong survival in vivo in xenograft models." (PMID 23874926, 2013).
glioma (continued). "In addition, another study suggested that GAS5, miR-196a-5p, and Forkhead Box Protein O1 (FOXO1) form a positive feedback loop in glioma stem cells." (PMID 39941145, 2025). "Notably, FOXO1 functions as a critical tumor suppressor by activating cell cycle arrest and apoptosis in glioma." (PMID 39516471, 2024). "Few studies have mentioned the oncogenic capabilities of FOXO1 as a therapeutic target in glioma." (PMID 37821870, 2023). "Given that many studies conducted up to now support the tumor suppressor role of FOXO1, restoring its expression may reverse glioma tumorigenesis in its early stages." (PMID 37821870, 2023). "The controversial role of FOXO1 in tumorigenesis is also seen in gliomas." (PMID 37821870, 2023). "Therefore, using CDK2 inhibitors was shown to increase the nuclear translocation of FOXO1 in U87 glioma cells more than in U251 cells." (PMID 37821870, 2023). "In addition, most of the pharmacological compounds which affect FOXO1 were shown to increase their expression in gliomas." (PMID 37821870, 2023). "Another study in glioma stem cells showed that GAS5 can also upregulate the other member of the FOXO family, namely FOXO1 via downregulating miR-196a-5p expression resulting in inhibition of cell proliferation, migration, invasion, and promotes apoptosis in glioma stem cells." (PMID 35736636, 2022). "Moreover, human glioma cell radiosensitivity can similarly be enhanced by LITAF via the FOXO1 pathway." (PMID 36061358, 2022). "Besides, the results of RNA pull-down and RIP assays demonstrated that DANCR pulled down FOXO1 and that DANCR enrichment by FOXO1 was elevated relative to that by IgG or Input, indicating the occurrence of binding between DANCR and FOXO1 in glioma cells." (PMID 35141227, 2021). "Collectively, these data demonstrate that miR‐5188 directly targets FOXO1 in glioma." (PMID 32902145, 2020). "miR‐5188 levels were negatively associated with FOXO1 mRNA levels (r = −0.3380, P = .0329), but positively correlated with c‐JUN mRNA levels (r = 0.2975, P = .0003) and SP1 mRNA levels (r = 0.2116, P = .0028) in the glioma specimens." (PMID 32902145, 2020). "In glioma samples, miR‐5188 expression was found to be an unfavourable factor and was positively associated with the mRNA levels of SP1 and c‐JUN, whereas negatively associated with the mRNA levels of FOXO1." (PMID 32902145, 2020). "GAS5 suppresses the malignancy of human glioma stem cells via a miR-196a-5p/FOXO1 feedback loop." (PMID 29552296, 2018). "The substantial presence of known glioma-associated genes in the neighborhood of FOXO1, PBX3 and CARHSP1 may indicate the additional presence of genes with currently unidentified roles in glioma." (PMID 28957313, 2017). "Thus, our data provide direct evidence that FOXO1 acts as a cancer suppressor in glioma cells via modulating oncogenic behaviors." (PMID 27835585, 2016). "The effect of FOXO1 on cell invasion in glioma cells was determined using transwell assay." (PMID 27835585, 2016). "Additionally, the decrease of FOXO1 mRNA level in the high-grade gliomas was greater than that in the low-grade gliomas." (PMID 27835585, 2016). "KLF4 knockdown up-regulated FOXO1 expression at both mRNA and protein levels in glioma cells." (PMID 27835585, 2016). "Thus, we further performed experiments to explore the biological functions of FOXO1 in glioma cells." (PMID 27835585, 2016). "Furthermore, for the analysis of overall survival (OS), glioma patients group with low FOXO1 protein level had significantly poorer OS than the patients group with high FOXO1 protein level." (PMID 27835585, 2016). "Restored FOXO1 expression inhibits glioma cells growth and invasion." (PMID 27835585, 2016). "To observe transcriptional regulation of FOXO1 expression in glioma, we analyzed the response elements of a cohort of transcription factors located within the two kilobase region upstream of transcription start site of FOXO1 gene." (PMID 27835585, 2016).
glioma (continued). "In summary, here we investigated the expression pattern and role of FOXO1 in glioma." (PMID 27835585, 2016). "Additionally, we found that KLF4 expression frequently increased in glioma tissues and negatively correlated with FOXO1 expression." (PMID 27835585, 2016). "Our study highlighted nuclear exclusion of FOXO1 in glioma progression." (PMID 23874926, 2013). "Furthermore, the expression level FOXO1 was downregulated in glioma." (PMID 39516471, 2024). "Besides, Western blotting revealed that miR‐5188 inhibition led to reduced protein levels of P‐PI3K, P‐AKT, CCND1, CDK4 and c‐JUN, but increased protein levels of FOXO1 in glioma cells with SP1 overexpression, suggesting that miR‐5188 was enhanced by SP1 through the PI3K/AKT pathway." (PMID 32902145, 2020). "Furthermore, we performed an exhaustive literature search to identify whether any of FOXO1 or CARHSP1’s immediate neighbors also exhibited particular expression patterns related to glioma." (PMID 28957313, 2017). "Therefore, we analyzed the effects of S109 on the phosphorylation of Foxo1 and Rb1 in glioma cells." (PMID 27733172, 2016). "Importantly, the negative association between KLF4 and FOXO1 levels was observed in glioma tissue samples." (PMID 27835585, 2016). "However, the precise expression pattern and role of FOXO1 in glioma remain elusive." (PMID 27835585, 2016). "Additionally, it has been demonstrated that FOXO1-induces G1 phase cell-cycle arrest in renal cell carcinoma and glioma cells due to inhibition of tumor suppressor phosphatase and tensin homolog deleted on chromosome ten (PTEN), via upregulation of the cyclin-dependent kinase inhibitor p27Kip1." (PMID 23029264, 2012). "Quinolinic acid affects the TME of gliomas by acting on N-Methyl-D-aspartic acid (NMDA) receptors and the forkhead box O1 (Foxo1)/peroxisome proliferator-activated receptor γ (PPARγ) signaling pathway, inducing a tumor-supportive phenotype in macrophages." (PMID 38930435, 2024). "However, the exact mechanism by which glioma downregulates FOXO1 remains unclear." (PMID 39516471, 2024). "Another study has revealed that in both GBM and lower-grade gliomas undergoing hypoxia (higher expression of HIF-1α,) the expression of FOXO1 is also elevated." (PMID 37821870, 2023). "In addition, PI3K/mTOR or FOXO1 inhibitors could prevent glycolysis in gliomas." (PMID 37821870, 2023). "Expression of miRNA-21 was increased and anti-tumorigenic genes (FoxO1, PTEN, and PDCD4) were decreased in exosomes within T. gondii-infected U87 glioma cells." (PMID 36180486, 2022). "IGF2BP2 and DANCR were highly expressed in glioma cells and tissues, whereas PID1 and FOXO1 were poorly expressed." (PMID 35141227, 2021). "The expression levels of PDL1 (CD274), FOXO1, and PRDM1 in the high-HIF1A-expression group were significantly higher in both glioblastoma (GBM) and lower-grade glioma." (PMID 34305618, 2021). "Collectively, IGF2BP2 inhibits PID1 expression through the DANCR/FOXO1 axis, inducing drug resistance in GBM cells, and promoting glioma progression." (PMID 35141227, 2021). "FOXO1 also enhanced the expression of migration and invasion inhibitory protein (MIIP), which decreased the migration and invasion of glioma cells." (PMID 33391419, 2021). "miR‐5188, FOXO1, c‐JUN and SP1 expression were measured to illustrate their potential correlations in glioma and healthy brain tissues." (PMID 32902145, 2020). "In the current investigation, we identified the important role of miR‐5188 in glioma by examining miR‐5188 expression in glioma and non‐tumour brain specimens and the correlations between the expression of miR‐5188, SP1, c‐JUN and FOXO1." (PMID 32902145, 2020). "In the current investigation, miR‐5188 was found to target the FOXO1 mRNA 3′UTR and inhibit its expression to augment cell proliferation, migration and invasion in glioma." (PMID 32902145, 2020).
glioma (continued). "Decreases in Akt1 levels mediate EMT and effect cell cycle by regulating proteins such as Foxo1, MMP2, p27Kip1 and p21Cip1 in cervical carcinoma and glioma." (PMID 27323412, 2016). "We firstly detected FOXO1 protein level in a series of human glioma cell lines and found that FOXO1 protein was relatively lowly expressed in the A172, U87MG, U118MG and U251MG glioma cell lines, compared with endogenous control β-Actin." (PMID 27835585, 2016). "Clinically, FOXO1 phosphorylation has been associated with disease progression in several cancers, including leukemia, alveolar rhabdomyosarcoma, prostate cancer, gastric cancer and soft tissue sarcoma, but its clinical and pathologic significance in glioma has not been investigated yet." (PMID 23874926, 2013). "Phosphatidylinositol 3 kinase (PI3K) signalling, necessary to stimulate glioma invasion and migration downregulates FOXP3 expression by sequestering FOXO1 and FOXO3a factors in the cytoplasm." (PMID 23888189, 2012). "Forced FOXO1 suppresses the cell growth through G2/M cell cycle arrest and increases apoptosis in glioma, whereas silencing of DANCR could repress the ubiquitination of FOXO1 in osteoblast differentiation and reduce the amount of DANCR bound to FOXO1." (PMID 35141227, 2021). "Studies indicate that FOXO1, PTEN, Akt, PI3K, and mTOR may be closely involved in chemotherapy resistance in glioma." (PMID 33391419, 2021). "FOXO1 promoted expression of PID1, and the binding of FOXO1 to the PID1 promoter could activate the transcription of PID1 in glioma stem cell." (PMID 35141227, 2021). "In a word, FOXO1 bound to PID1 promoter, promoting transcription of PID1 in glioma." (PMID 35141227, 2021). "FOXO1 upregulates the expression of the protein phosphotyrosine interaction domain containing 1 (PID1), thereby inhibiting the tumorigenicity and growth of glioma stem cells." (PMID 35141227, 2021). "In this study, we attempted to identify the interaction between FOXO1 and PID1 in glioma." (PMID 35141227, 2021). "Besides, FOXO1 knockdown elevated protein levels of P‐PI3K, P‐AKT, CDK4, CCND1, c‐JUN, N‐cadherin and vimentin in glioma cells." (PMID 32902145, 2020). "Our investigation demonstrates that miR‐5188 could function as a tumour promoter by directly targeting FOXO1 and participating in SP1‐mediated promotion of cell growth and tumorigenesis in glioma." (PMID 32902145, 2020). "Furthermore, the expression pattern of FOXO1, SP1 and c‐JUN in glioma samples and the correlations between FOXO1, c‐JUN, SP1 and miR‐5188 levels suggested an vital role of miR‐5188 in glioma development through FOXO1, c‐JUN and SP1 dysregulation." (PMID 32902145, 2020). "In the GAS5/miR-196a-5p/FOXO1/PID1 (MIIP) pathway of glioma stem cells, FOXO1 promotes GAS5 transcription and forms a positive feedback loop that regulates the biological behavior of glioma stem cells." (PMID 30736838, 2019). "Results indicated that FOXO1 mRNA level significantly decreased in the majority of primary glioma tissue samples, compared with the matched non-tumor brain tissues." (PMID 27835585, 2016). "In this manuscript, we report that the inhibition of CRM1 by S109 might significantly promote the nuclear retention of Foxo1, and our results indicate that redirecting Foxo1 to the nucleus by inhibiting CRM1 might be an effective approach for treating gliomas." (PMID 27733172, 2016).